MYOZ1 (myozenin 1)
Description:
Myozenins may serve as intracellular binding proteins involved in linking Z-disk proteins such as alpha-actinin, gamma-filamin, TCAP/telethonin, LDB3/ZASP and localizing calcineurin signaling to the sarcomere. Plays an important role in the modulation of calcineurin signaling. May play a role in myofibrillogenesis.
Synonyms: MYOZ; FATZ; CS-2
Tractability: No criterion of Open Targets' tractability assessment is met for any kind of drug.
Gene: Protein-coding gene on chromosome 10 (73,631,571 to 73,642,103, reverse strand). Ensembl gene ENSG00000177791.
Subcellular location: Nucleus; Cell projection, pseudopodium
Gene Ontology:
Molecular function: actinin binding; FATZ binding; molecular condensate scaffold activity; protein binding; actin binding; protein serine/threonine phosphatase inhibitor activity; telethonin binding
Biological process: myofibril assembly; negative regulation of calcineurin-NFAT signaling cascade; negative regulation of skeletal muscle tissue regeneration; negative regulation of transcription by RNA polymerase II; sarcomere organization; skeletal muscle fiber adaptation; skeletal muscle tissue development; wound healing
Cellular component: actin cytoskeleton; Z disc; nucleus; pseudopodium
Genetic constraint (gnomAD): Loss-of-function variants: 20 observed, 29.17 expected, observed/expected ratio (o/e) 0.69, 90% interval 0.48 to 1. The upper end of that interval is the gene's LOEUF score, 1, which puts it in group 4 of 6, group 1 being the genes least tolerant of losing a copy. Missense variants: 371 observed, 392.98 expected, observed/expected ratio (o/e) 0.94, 90% interval 0.87 to 1.03. Synonymous variants: 144 observed, 154.79 expected, observed/expected ratio (o/e) 0.93, 90% interval 0.81 to 1.07.
Homologues: Orthologues: chimpanzee MYOZ1 (99% identical), macaque MYOZ1 (99% identical), guinea pig MYOZ1 (94% identical), rabbit MYOZ1 (94% identical), pig MYOZ1 (93% identical), dog MYOZ1 (92% identical), mouse Myoz1 (90% identical), rat Myoz1 (90% identical), tropical clawed frog myoz1 (64% identical), zebrafish myoz1a (47% identical), zebrafish myoz1b (34% identical). Paralogues in human: MYOZ2 (29% identical), MYOZ3 (23% identical).
Diseases named in the same sentence as MYOZ1 in open-access papers:
MYOZ1 is named in the same sentence as 20 diseases in open-access papers, as found by Europe PMC text mining. Sharing a sentence is not in itself a finding about the gene and the disease. The quoted sentences say what the papers report.
atrial fibrillation (5 papers, 2013 to 2025). A disorder characterized by an electrocardiographic finding of a supraventricular arrhythmia characterized by the replacement of consistent P waves by rapid oscillations or fibrillatory waves that vary in size, shape and timing and are accompanied by an irregular ventricular response. "A compelling example is the association between MYOZ1 expression and atrial fibrillation." (PMID 33554857, 2021). "However, expression of MYOZ1 in left and right atria has been reported as a cause of a type of arrhythmia—atrial fibrillation." (PMID 30517173, 2018).
cardiomyopathy (2 papers, 2023 to 2026). A disease of the heart muscle or myocardium proper. "These include known Mendelian cardiomyopathy risk genes such as FLNC and ACTN2, and novel regulatory candidates like CAMK2D, LMF1, MYOZ1, SKI, SYNPO2L, and TKT." (PMID 41646816, 2026).
muscular dystrophy (2 papers, 2022 to 2023). Muscular dystrophy (MD) refers to a group of more than 30 genetic diseases characterized by progressive weakness and degeneration of the skeletal muscles that control movement. "Because the MYOZ1 gene is closely related to muscle formation, mutations in the MYOZ1 gene can be associated with muscular dystrophy and neuromuscular myopathy." (PMID 37627391, 2023). "Since the MYOZ1 gene is closely related to muscle formation, mutations in the gene encoding calsarcin-2 can be associated with muscular dystrophy and neuromuscular myopathy." (PMID 36140742, 2022).
dilated cardiomyopathy (1 paper, 2020). Cardiomyopathy which is characterized by dilation and contractile dysfunction of the left and right ventricles. "Mutations in MYOZ1 were found in the patient with dilated cardiomyopathy." (PMID 32902410, 2020).
Fanconi anemia (1 paper, 2022). Fanconi anemia (FA) is a hereditary DNA repair disorder characterized by progressive pancytopenia with bone marrow failure, variable congenital malformations and predisposition to develop hematological or solid tumors. "Similar to FBXL21 ubiquitinating MYOZ1 and TCAP, another E3 ligase, the FANCL subunit of the FA (Fanconi anemia) core complex, has been shown to monoubiquitinate two interacting proteins, namely FANCD2 and FANCI." (PMID 36574402, 2022).
oral squamous cell carcinoma (1 paper, 2019). "Some studies have shown that MYOZ1 has correlation with oral squamous cell carcinoma and it could be regarded as a molecular target for cancer applications." (PMID 31888692, 2019).
cancer (2 papers, 2019 to 2022). A tumor composed of atypical neoplastic, often pleomorphic cells that invade other tissues. "The expression of KHDRBS2 and MYOZ1 was downregulated in the LUAD cancer samples compared with that in the para-tumor normal samples, whereas the expression of BARX1, ENTPD2, and GFRA3 was upregulated in LUAD cancer tissues." (PMID 36353226, 2022).
infection (2 papers, 2016 to 2024). The state of being infected such as from the introduction of a foreign agent such as serum, vaccine, antigenic substance or organism. "Down-regulated proteins included cystatin-B, dystroglycan, and mucin-1 in the early stage of infection (36 and 42 h PC), and myozenin-1 and alpha-lactalbumin at the subsequent stage (57 and 81 h PC)." (PMID 27412694, 2016). "Genes encoding protein components of the cytoskeleton (NEB, MYOM2, MYOZ1, and MYBPC1) and surfactant proteins (A1, C, and D) were among the most significantly downregulated genes upon infection with swH1N1." (PMID 39247193, 2024).
tumor (1 paper, 2022). "Specifically, the expression of KHDRBS2 and MYOZ1 was downregulated in LUAD tumor samples." (PMID 36353226, 2022).
MYOZ1 also shares sentences with these, for which no sentence is quoted: Arrhythmia (2 papers); atherosclerosis (1); Cachexia (1); cardiac hypertrophy (1); diabetes (1); Hyperglycemia (1); Insulin resistance (1); metabolic syndrome (1); myopathy (1); sarcopenia (1); type 2 diabetes (1).